IL1B (interleukin 1 beta)
Diseases named in the same sentence as IL1B in open-access papers (continued):
Sharing a sentence is not in itself a finding about the gene and the disease.
breast cancer (continued). "Moreover, toxicity against breast cancer cells strongly correlated with cytokine inhibition with p = 0.023 for IL-1β and p < 0.001 for TNF-α, IL-6, IL-8, and IL-10." (PMID 31581678, 2019). "The roles of IL-1β in the invasion of breast cancer were extensively explored." (PMID 31492049, 2019). "Furthermore, we analysed a cohort of 79 breast cancer patients and quantified the staining intensity and the abundance of IL-1β-expressing fibroblasts." (PMID 31558756, 2019). "For instance, IL-1β was found to be a master cytokine in the development of breast cancer." (PMID 31492049, 2019). "The synergistic upregulation of IL-6 secretion in response to OSM and IL-1β suggests that these cytokines may be using separate pathways to promote IL-6 in breast cancer cells." (PMID 31007849, 2019). "Blockage of IL-1β could induce antitumor immunity and resulted in breast cancer regression by activating CD8+ lymphocytes." (PMID 31492049, 2019). "Interestingly, it was recently reported that in human breast cancer cell lines, IL-1β induced OPG secretion, indicating a novel role for OPG as a mediator of inflammation-promoted breast cancer progression." (PMID 30736365, 2019). "In addition, pro-inflammatory effects of IL-1B also promote metastasis: In a spontaneous in vivo model of breast cancer, tumour cells induce systemic inflammation by producing IL-1B, which stimulates IL-17 production by γδ T cells." (PMID 29760166, 2018). "In vitro studies have recently shown that primary breast cancer cells co-cultured with monocytes display increased IL-1B, IL8 and MMPs, suggesting that inflammation and therefore the recruitment of immune cells support the development of breast cancer during the early stages." (PMID 29760166, 2018). "Interestingly, numerous studies demonstrated that cytokines and adipokines such as IL-6, IL-1β, TNFα and Leptin are major factors in breast cancer progression." (PMID 29930291, 2018). "Co-culture of a human breast cancer cell line, with suppressed ability to form metastases, with osteoblasts resulted in faster growth of breast cancer cells attached to the matrix made by the osteoblasts when stimulated with IL-1B and TNFa." (PMID 29760166, 2018). "IL-1B was present in the supernatant of metastatic breast cancer cells." (PMID 29760166, 2018). "In vitro evidence from MCF7 breast cancer cells suggests that this may, in part, be due to, IL-1B-regulating breast cancer cell invasion by stimulating production of MMP-9 via focal adhesion kinase 1 FAK and the proto-oncogene tyrosine-protein kinase Src." (PMID 29760166, 2018). "Because IL-1B regulates bone homeostasis and contributes to enhanced bone resorption upon inflammation, it is possible to speculate that in breast cancer metastasis, IL-1B alters bone turnover in favour of the vicious cycle." (PMID 29760166, 2018). "Therefore, inhibiting IL-1B signalling is a potential new therapeutic strategy to simultaneously block angiogenesis and dampen inflammation, impairing breast cancer bone metastasis." (PMID 29760166, 2018). "The inhibition of IL-1R1 and reduced bone metastasis in our mouse model shows the role of this signalling axis in breast cancer metastasis to bone, but further studies are needed to elucidate whether IL-1B and/or IL-1A are primarily involved in this process." (PMID 29760166, 2018). "How breast cancer cells, chemokines and cytokines, including IL-1B affect these cells may be a fundamental factor in determining whether tumour cells in bone are able to progress to overt metastases." (PMID 29760166, 2018). "Recent in vitro data indicate that IL-1B and not IL-1A is the relevant cytokine linked to dormancy of breast cancer cells in this environment." (PMID 29760166, 2018).
breast cancer (continued). "Recent evidence from our group has shown that breast cancer cells with increased ability to metastasise in bone (MDA-IV) display higher IL-1B expression, compared to its correspondent parental line, suggesting that IL-1B expression correlates with enhanced metastatic potential." (PMID 29760166, 2018). "A further reinforcement of an immunosuppressive TME in breast cancer may be induced by high levels of IL-1β." (PMID 30154786, 2018). "There is accumulating evidence indicating the presence of a peritumoural inflammatory infiltrate in BC, which may reflect, at least in part, an antitumour immune response.IL-1A and IL-1B expression was increased in human breast cancer tissues." (PMID 29719585, 2018). "Based on these findings we hypothesized that IL1B modulates breast cancer invasion and metastasis by OPG regulation." (PMID 28143606, 2017). "Exogenous IL1B can induce OPG expression in human breast cancer and other cancer cell lines." (PMID 28143606, 2017). "We hypothesized that macrophages could be a source of IL1B that would further stimulate OPG secretion in breast cancer cells." (PMID 28143606, 2017). "In this current study, we investigate the IL1B-mediated upstream signaling events involved in OPG expression, look into the involvement of macrophages in OPG expression, and examine the link between OPG and IL1B as a novel inflammatory pathway promoting breast cancer metastasis." (PMID 28143606, 2017). "We asked whether macrophages could serve as an IL1B source to influence OPG expression in breast cancer cells." (PMID 28143606, 2017). "Treatment with exogenous IL1B elevated the IL1B mRNA levels in the breast cancer cells." (PMID 28143606, 2017). "Also, we show that IL1B-mediated breast cancer cell invasion, and the induction of MMP3 and IL1B itself, occurs in an OPG-dependent manner." (PMID 28143606, 2017). "Macrophages, but possibly also breast cancer cells themselves, may serve as local IL1B sources to influence OPG secretion." (PMID 28143606, 2017). "Furthermore, the significant correlation between MCT2 and IL-1β/LCN2 expressions in clinical breast cancer specimens supports the role of an MCT2-mediated oncogenic pathway in breast cancer progression." (PMID 28281525, 2017). "We therefore asked whether OPG was important in IL1B-mediated MMP3 induction in breast cancer cells." (PMID 28143606, 2017). "Thus, within the inflammatory tumor microenvironment, IL-1β, together with other cytokines and growth factors, increases breast cancer cell aggressiveness in a TG2-dependent manner." (PMID 27609180, 2016). "Thus, within the inflammatory tumor microenvironment, IL-1β, together with other cytokines and growth factor signals, increases breast cancer cell aggressiveness in a TG2-dependent manner." (PMID 27609180, 2016). "Together, these results show that estrogenic GPER signalling may regulate IL1β expression also in CAFs derived from a breast cancer metastasis." (PMID 27072893, 2016). "Whereas IL-1B expression has been implicated in metastatic behaviour of breast cancer cells in vitro, no functional in vivo studies have been published and no specific link to bone metastasis has been explored." (PMID 27765923, 2016). "In terms of the relevance of IL-1β to breast cancer cell aggressiveness, breast cancer metastasis suppressor 1 has been shown to up-regulate miR-146, which targets key IL-1 receptor signaling molecules, including IRAK1 and TRAF6, and suppresses the metastasis of breast cancer cells." (PMID 27609180, 2016). "We next evaluated the effect of IL-1β stimulation on MCF7 breast cancer cells." (PMID 27609180, 2016). "In addition, a study showed that co-culture of macrophages with breast cancer cell lines enhances IL-1β expression, IL-1β-dependent induction of cyclooxygenase (COX)-2 and tumor progression." (PMID 27487154, 2016).
breast cancer (continued). "Moreover, rottlerin was reported to enhance IL-1β (interleukin-1β)-induced COX-2 (cyclooxygenase-2) expression via activation of p38 MAPK (mitogen-activated protein kinases) in breast cancer cells." (PMID 27626499, 2016). "To confirm that inhibition of HIF-1α resulted in upregulation of NFκB in hypoxic breast cancer cells in the presence of IL-1β, we decided to perform similar experiments by using Topotecan, a topoisomerase inhibitor which has been described also as a pharmacological inhibitor of HIF-1α." (PMID 26696754, 2015). "Indeed, breast cancer progression is actively supported by inflammatory components, including IL-1β, and by the hypoxia-inducible factor- (HIF-) 1α." (PMID 26696754, 2015). "IL-1β activates a variety of proinflammatory pathways, including NFκB, whose relevance in cell migration has been recognized in several cell types, including breast cancer." (PMID 26696754, 2015). "Altogether, these data suggest that metastatic breast cancer cells secrete IL-1β, and maybe other unidentified factors, to promote the release of chemokines by MSCs, which in turn could enhance the invasion properties of cancer cells." (PMID 26362269, 2015). "For example, blocking IL-1β signaling in metastatic melanoma cells and in breast cancer may be beneficial because IL-1β is indicated to promote tumor progression and metastasis in these tumors." (PMID 24474192, 2014). "Likewise, among three patients with OC and a family history of ovarian and/or breast cancer, average urinary IL-1β levels were elevated (6.33 pg/ml) compared to OC patients without a family history of ovarian and/or breast cancer (1.16 pg/ml)." (PMID 25403235, 2014). "While having cytotoxic effects when acutely administered to tumors, the chronic presence of TNFα in breast tumor sites leads to increased tumor aggressiveness; IL-1β up-regulates processes that contribute to higher angiogenesis, tumor growth and progression in breast cancer." (PMID 24598028, 2014). "The IL1B-rs1143627 variant has been associated with increased breast cancer risk in Asian populations, but has not been examined in either an EA or AA population." (PMID 23991131, 2013). "Moreover, IL-1β has been found to combine with estrogen receptor (ER)α in breast cancer cells, resulting in transcriptional activation." (PMID 23704929, 2013). "Among postmenopausal women, two SNPs in high LD in the IL1B gene, rs1143627 and rs16944, were associated with an increased risk of breast cancer in EA, but not AA women." (PMID 23991131, 2013). "It has been shown that IL1β may combine with the estrogen receptor-alpha, resulting in the enhancement of transcriptional activation in breast cancer cells." (PMID 23049925, 2012). "The findings on IL-1β strongly support the possibility that when the tumor-derived and/or microenvironment-derived characteristics have higher cancer-promoting properties, IL-1β can further promote progression-related processes in breast cancer." (PMID 21486440, 2011). "Based on the increased expression of IL-1β following FGFR1 activation and the link between IL-1β and breast cancer, we hypothesised that IL-1β may be an important factor in the formation of iFGFR1-induced proliferative lesions." (PMID 19393083, 2009). "Because IL-1β can promote these properties in breast cancer cells, we hypothesised that IL-1β may act cooperatively with another oncogenic stimulus to promote tumourigenic changes." (PMID 19393083, 2009). "In the present study, the IL1RN long/2 gene polymorphism was independently associated with an unfavourable prognosis in breast cancer patients, while presence of the mutant alleles of IL1A -889 and IL1B +3953 were only associated with a shortened overall survival in a univariate analysis." (PMID 19267917, 2009).
breast cancer (continued). "This indicates that IL-6 is not the downstream mediator of IL-1β-mediated MDSC infiltration in the 4T1 breast cancer model, and suggests that another downstream target of IL-1β may modulate MDSC infiltration in this model." (PMID 19888452, 2009). "However, the mechanisms by which IL-1β acts on tumour cells and/or cells within the stroma to promote breast cancer in vivo are not well understood." (PMID 19393083, 2009). "The aim of this study was to evaluate polymorphisms in specific cytokine genes [IL1A +4845G>T, IL1B -511C>T, IL1B +3954C>T, IL1RN +2018T>C, IL4R -1902A>G, IL6-174G>C and IL10-1082G>A] in a case control model to determine any associations with breast cancer susceptibility, severity and survival." (PMID 16842617, 2006). "Additionally, stimulation by cytokines like interleukin-1β (IL-1β), which is actively synthesized in breast cancer, could increase the expression of acetylcholinesterase mRNA and, consequently, its enzymatic activity." (PMID 40003620, 2025). "Furthermore, IL-1β genetic polymorphisms and TNBC susceptibility and breast cancer indicate the diagnostic and prognostic potential of these variants in postmenopausal individuals with breast cancer." (PMID 40584290, 2025). "Thus, OPG acts as a crucial mediator in the tumor-promoting actions of IL-1B in breast cancer." (PMID 39941709, 2025). "Additionally, co-culture of breast cancer cell lines and human femur tissue derived from patients undergoing hip replacement surgery induced the upregulation of IL-1β and leptin and promoted the colonization of cancer cells within the bone marrow adipose tissue." (PMID 39858071, 2025). "Additionally, many markers we observed that defined our monocyte clusters (FABP5, FN1, IL1RN, CCL3, CCL4, CXCL8, CXCL3, IL1B) during transient, short-term CM stimulation, were elevated in either PD-L1pos or PD-L1neg TAMs isolated and sequenced from breast cancer." (PMID 40176808, 2025). "For instance, Leptin and Insulin levels decreased, particularly in Breast cancer patients, whereas Colorectal cancer patients exhibited a reduction in pro-inflammatory cytokines such as IL-1β, IL-6, IL-8, and TNF-α, even in the absence of weight loss and bioimpedential feature changes." (PMID 41409302, 2025). "Moreover, EGF increases breast cancer cell migration in synergy with IL-1β." (PMID 38438872, 2024). "Moreover, when breast cancer cells arrive in the bone microenvironment there is an upregulation of IL-1B which promotes the creation of a conducive niche for metastatic breast cancer cells as well as stimulating initiation of the vicious cycle of bone metastasis." (PMID 38800348, 2024). "Furthermore, there is a growing amount of evidence suggesting that inhibiting IL-1B production or activation of its’ receptor, IL-1R1, maybe effective therapeutic strategies for preventing/treating breast cancer bone metastasis." (PMID 38800348, 2024). "Activation of TNF-α and IL-1β in breast cancer can lead to abnormal genetic transcription, which is beneficial to cancer cells and aids in their resistance to apoptosis, making Nf-κB a critical target in breast cancer therapeutics, particularly in the more aggressive subtypes." (PMID 39728433, 2024). "Anti-IL-1β mAbs could enhance the efficacy of PD-1 blockades against breast cancer." (PMID 38520006, 2024). "Additionally, a recent study indicated that bone marrow-derived IL-1B promoted breast cancer cell colonisation in the bone by activation of intracellular NF-κB/CREB signalling in breast cancer cells, resulting in autocrine Wnt signalling and cancer stem cell (CSC) colony formation." (PMID 38800348, 2024). "Given the overexpression of HSP90 in malignancies such as breast cancer and its documented role in facilitating the inclusion of molecules like IL-1β and RAB22A-NEOF1 into vesicles, it is plausible that LAP-TGF-β1 might be incorporated into exosomes through an interaction with HSP90A." (PMID 38664722, 2024).
breast cancer (continued). "The effector cytokines of inflammasomes can be different when it comes to spontaneous breast cancer mice models where genetic blockage of IL-1α/IL-1R1 signal develops higher tumor burden and increased mortality rate implying similar roles of IL-1α, IL-1β, and IL-18 in tumorigenesis." (PMID 36932407, 2023). "Ascites proinflammatory cytokines IL-1β, IL-6, TNF-α were increased in model mice, but were significantly reduced following EFL1 or DOX administration, which demonstrates that EFL1 is able to decrease the generation of proinflammatory cytokines caused by breast cancer liver metastasis." (PMID 37709489, 2023). "In addition, NLRP3 inhibition proved to be protective against IL-1β upregulation in peritumoral astrocytes in the mouse breast cancer brain metastasis model, resulting in an approximately 75% decrease in the percentage of IL-1β- and GFAP-double-positive pixels." (PMID 37749707, 2023). "They found that cisplatin could induce MDA-MB-231 cell pyroptosis via upregulating the lnc RNA MEG3 and activating the NLRP3/caspase-1/GSDMD pathway, which would accelerate the inflammatory cytokines (IL-18 or IL-1β) release and effectively treat breast cancer." (PMID 38016064, 2023). "Among them, NLRP3 inflammasomes could mediate infiltration of CD11b+Gr1+ immune cells into mammary tumor tissues, and IL-1β could promote mammary tumor progression and tumor cell metastasis to the lung by upregulating adhesion molecules expression in primary tumors and metastatic sites." (PMID 37020871, 2023). "At the same time, a recent finding addressed that IL-1β maintains metastasis-initiating cells (MICs) in a high mesenchymal state, which facilitates MICs invasion but prevents colonization, implicating that IL-1β functions both pro- and anti-tumor effects in breast cancer metastasis." (PMID 36823153, 2023). "The present results suggest that breast cancer survivors with PD have worse cognitive functioning based on a cognitive screening test and lower quality of life than the PD group, and significantly higher levels of IL‐1β, TNF‐α, and IL‐4, compared to the patients with NPD." (PMID 36965094, 2023). "MDD is associated with higher circulating levels of inflammatory cytokines, such as interleukin (IL)‐6, IL‐8, IL‐1β, TNF‐α, soluble IL‐2 receptor (sIL‐2R), and C‐reactive protein (CRP), which promote cellular proliferation in breast tissue and have also been linked to development of breast cancer." (PMID 35852181, 2023). "Thus, among the pro-inflammatory cytokines in breast cancer, the content of IL-1β, IL-2, and IL-6 increased (+16.1%, +25.0%, and +12.7%, respectively), while for TNF-α, MCP-1, IL-8, and IL-18, the content decreased (−36.2%, −23.8%, −15.0%, and −12.1%, respectively)." (PMID 36286034, 2022). "For instance, in breast cancer, NLRP3 inflammasome-induced IL-1β production promotes infiltration with immunosuppressive myeloid-derived suppressor cells (MDSCs) and tumor-associated macrophages (TAMs), generating a TME favoring breast cancer progression and metastasis." (PMID 35740272, 2022). "Therefore, we speculate that inhibiting downstream targets of IL-1 (IRAK1, TRAF6, IKK) has effects on reducing osteoclastic bone resorption, while IL1β inhibition not only reduces osteoclastic bone resorption but also blocks breast cancer metastasis to bone." (PMID 36230739, 2022). "Considering the reported IL-1β signal reported in breast cancer, we sought to investigate whether NLRP3 activation is involved in the production of IL-1β in breast cancer and whether its inhibition would reduce the increased IL-1β signal and enhance anti-PD-1 therapy." (PMID 35631400, 2022). "In addition, under sympathetic stimulation, osteoblast derived vascular endothelial growth factor (VEGF) and IL-1β was able to modulate endothelial cells to facilitate breast cancer cell extravasation from circulation into the bone marrow niche, both in vitro and in vivo." (PMID 35243294, 2022).